NLRP3 (NLR family pyrin domain containing 3)
Diseases named in the same sentence as NLRP3 in open-access papers (continued):
Sharing a sentence is not in itself a finding about the gene and the disease.
endothelial dysfunction (continued). "Therefore, our study is the first to demonstrate that Sil improves endothelial dysfunction by blocking the NLRP3/caspase-1 pyroptosis pathway." (PMID 37636019, 2023). "Finally, at the endothelial level, ROS can be defined as the point of contact between NLRP3 and endothelial dysfunction." (PMID 37507935, 2023). "Additionally, the activation of the NOD-like receptor protein 3 (NLRP3) inflammasome by TMAO has been suggested as one of the mechanisms for the development of endothelial dysfunction and hypertension." (PMID 37089429, 2023). "For example, it may protect endothelial dysfunction through inhibiting Nox4-responsive oxidative stress and ROS-sensitive NLRP3 signaling pathway under high glucose stress both in vivo and vitro." (PMID 37049509, 2023). "By provoking endothelial inflammation, NLRP3 activation worsens endothelial dysfunction." (PMID 37273529, 2023). "Oxidative stress, mitochondrial dysfunction, and immune activation may also trigger a common signaling pathway of NLRP3 inflammasome activation, thereby exacerbating endothelial dysfunction." (PMID 37763063, 2023). "The NLRP3 inflammasome promotes disruption of tight junctions in endothelial cells resulting in endothelial dysfunction and may also induce ventricular arrhythmias in heart failure with preserved ejection fraction." (PMID 37626809, 2023). "Therefore, it can be concluded that NLRP3 inflammasome in endothelial cells is responsible for various diseases through aggravating endothelial dysfunction under pathophysiological conditions." (PMID 37175227, 2023). "In the present study, we have evaluated whether a positive feedback of IL-1β in the NLRP3 inflammasome via NF-κB could promote human endothelial senescence in vitro and murine endothelial dysfunction in vivo." (PMID 35111374, 2022). "In summary, the present study demonstrated that EC-specific Smpd1 gene overexpression enhanced the production of ceramide and the formation of MR redox signaling platforms, promoted the activation of endothelial NLRP3 inflammasomes, and thereby resulted in endothelial dysfunction and atherogenesis." (PMID 36252682, 2022). "ROS are mainly derived from endoplasmic reticulum (ER) stress, damaged mitochondria, and NADPH oxidase, and can trigger the activation of the NLRP3 inflammasome in endothelial cells, bridging the interaction between the NLRP3 inflammasome and endothelial dysfunction." (PMID 35406642, 2022). "We suggest that interfering with NLRP3 inflammasome activation may be a feasible strategy to treat DENV-induced endothelial dysfunction." (PMID 36091000, 2022). "Besides, the NLRP3 inflammasome is a critical arbitrator of endothelial dysfunction-related inflammatory diseases, such as atherosclerosis, myocardial I/R injury, coronary arteritis, and ischemic stroke." (PMID 36092165, 2022). "We hypothesized that microgravity exposure induces mitophagy/mitochondrial dysfunction in HUVECs via ER stress, thereby alleviating endothelial dysfunction by inhibiting NLRP3 inflammasome activation." (PMID 35874841, 2022). "Globally, these results point at NLRP3 inflammasome as a main mediator of endothelial dysfunction and premature vascular aging in those pathological conditions in which excess IL-1β may impact the vasculature." (PMID 35111374, 2022). "Summary, ROS link the interaction between the NLRP3 inflammasome and endothelial dysfunction." (PMID 35844498, 2022). "The SGLT2 inhibitor drug class has been shown to exert anti-inflammatory actions by suppressing the activation of P3 receptor inflammasome activity (NLRP3), anti-fibrotic affects by stimulating M2 macrophages and inhibiting myofibroblast differentiation and improves endothelial dysfunction." (PMID 35327323, 2022). "Furthermore, CIRP was disclosed to induce acute lung injury and endothelial dysfunction via activation of endoplasmic reticulum (ER) stress and NLRP3 inflammasome." (PMID 35531472, 2022).
endothelial dysfunction (continued). "In this study, we evaluated if there is positive feedback of IL-1β on the NLRP3 inflammasome and whether this loop could promote human endothelial senescence in vitro, and endothelial dysfunction in vivo, using a murine experimental model." (PMID 35111374, 2022). "Because inflammasome-mediated pyroptosis was determined to be major RCD involved in DENV- and rEIII-induced endothelial dysfunction, we further explored whether suppression of the Nlrp3 inflammasome through inhibition would attenuate this dysfunction." (PMID 33717109, 2021). "Meanwhile, the interactions between endothelial dysfunction, oxidative stress, and the NLRP3 inflammasome-regulated pathways may improve the treatments of inflammation-related disorders, such as PE." (PMID 34831052, 2021). "Therefore, NLRP3 inflammasome is regarded as a therapeutic target of septic endothelial dysfunction and its inhibition mediates the cytoprotective effects in LPS-induced HUVECs injury by Procyanidin B2." (PMID 34011327, 2021). "Interestingly, an inflammasome-independent role of NLRP3 has also been reported in the endothelial dysfunction that is induced by high salt consumption." (PMID 33494430, 2021). "A better understanding of the interactions between endothelial dysfunction and the NLRP3 inflammasome-regulated pathways may open up a new avenue for effective treatment of cardiovascular complications in metabolic diseases including T2DM." (PMID 33546399, 2021). "However, below, we present those miRNAs that are altered in T2DM and are also known to be involved in either NLRP3 inflammasome activation or endothelial dysfunction." (PMID 33546399, 2021). "Activation of the NLRP3 inflammasome in endothelial cells under pathophysiological conditions may aggravate endothelial dysfunction, leading to various diseases." (PMID 34331512, 2021). "Moreover, the role of neutrophil extracellular traps and NLRP3 inflammasome as inflammatory mechanisms contributing to endothelial dysfunction has recently been unveiled and is under further investigation." (PMID 34356845, 2021). "Furthermore, our data suggest that 13-MB attenuates endothelial dysfunction by inhibiting NLRP3 inflammasome activation via autophagy induction." (PMID 31993073, 2020). "Meanwhile, the interactions between endothelial dysfunction and the NLRP3 inflammasome-regulated pathways may open up a new avenue for the treatment of cardiovascular diseases." (PMID 32948742, 2020). "We next used a human cell culture model to gain more insight into the cellular mechanisms by which visfatin/eNampt could promote endothelial dysfunction, focusing on pro-inflammatory pathways and NLRP3-inflammasome activation." (PMID 32214150, 2020). "We attempted to confirm whether 13-MB improves endothelial dysfunction and whether it is related to the NLRP3 inflammasome and autophagy." (PMID 31993073, 2020). "The NLRP3 inflammasome can affect the production of NO, leading to endothelial dysfunction." (PMID 33633569, 2020). "In addition, ChCs induced severe endothelial dysfunction in coronary arteries of Nlrp3+/+ mice, compared with the coronary arteries of transgenic Nlrp3−/− mice." (PMID 32508013, 2020). "All these drugs ameliorate endothelial dysfunction by inhibiting NLRP3 inflammasome activation." (PMID 32948742, 2020). "In addition, activation of endothelial NLRP3 inflammasome was partially correlated with lysosomal disruption in coronary arteritis, which resulted in endothelial dysfunction." (PMID 32226786, 2020). "In addition, in order to confirm the causal association between NLRP3 inflammasome activation and endothelial dysfunction, we injected NLRP3-AAV to inhibit the expression of NLRP3." (PMID 33633569, 2020). "This study unraveled a novel mechanism of aspirin in ameliorating endothelial dysfunction by blocking redox signaling and NLRP3 inflammasome activation, providing a new viewpoint on the clinical potential of aspirin in the early prevention of cardiovascular diseases." (PMID 32948742, 2020).
endothelial dysfunction (continued). "Since the NLRP3 inflammasome activation yields IL-1β 14,23 we analysed whether the blockade of IL-1 receptors could interfere with visfatin/eNampt-induced endothelial dysfunction." (PMID 32214150, 2020). "The activation of NLRP3 inflammasome may lead to the development of endothelial dysfunction and further accelerate the injury of vascular." (PMID 31412804, 2019). "In mice P2X7 is involved in endothelial dysfunction and may elicit the endothelial release of IL-1β19, which in PLs was enhanced by stimulation of NLRP3 with exogenous ATP20." (PMID 28687781, 2017). "Thus, the NLRP3 inflammasome plays a central role in endothelial dysfunction in response to various stimuli and therefore blocking this inflammasome or its key effectors has shown promise for diabetic therapy." (PMID 29207644, 2017). "This study is aimed to determine whether visfatin‐induced Nlrp3 inflammasome activation results in endothelial dysfunction or injury by disrupting inter‐endothelial junctions." (PMID 26293846, 2015). "Therefore, it is hypothesized that P. g-OMVs may contribute to the development and progression of As by inducing endothelial dysfunction through the modulation of the mitochondrial dysfunction-NLRP3 inflammasome-cellular pyroptosis pathway." (PMID 40256625, 2025). "Apart from activating NF-κB, TMAO also activates NLRP3 inflammasome leading to a proinflammatory milieu that has been demonstrated in human aortic endothelial cells as well as carotid artery endothelial cells implicating TMAO to contribute to endothelial dysfunction and CVD." (PMID 37626809, 2023). "Moreover, resveratrol could alter the expression of the NLRP3 inflammasome, which is critically involved in endothelial dysfunction and oxidative stress, in many organs." (PMID 37375772, 2023). "NLRP3 inflammasome activation may lead to endothelial dysfunction." (PMID 37375772, 2023). "However, (i) whether NETs have a pathogenic function in DKD, (ii) whether NLRP3 inflammasome and NET formation interact in the pathogenesis of DKD, and (iii) whether NETs contribute to glomerular endothelial dysfunction in DKD all remain unknown." (PMID 35889923, 2022). "In addition, expanding research into the role of NLRP3 in endothelial dysfunction may enrich the understanding of several inflammatory diseases." (PMID 34831052, 2021). "We present evidence of the importance of the endothelial dysfunction as the first key step to activating the inflammasome, which suggests that suppressing the NLRP3 inflammasome could be a new approach in depletion hyperglycemic toxicity and in averting the onset of vascular complications in T2DM." (PMID 33546399, 2021). "Therefore, we speculated that the upregulation of the Nrf2 pathway can decrease CSE-mediated pyroptosis through the ROS/NLRP3 axis and may alleviate endothelial dysfunction." (PMID 33839695, 2021). "In addition, in vitro mechanistic studies indicate that TMAO can induce vascular inflammation and endothelial dysfunction through activating NLRP3 inflammasome and the mitogen-activated protein kinase/nuclear factor-kappa B pathway, which also plays a critical role in thrombus formation." (PMID 34650427, 2021). "Also, we hypothesized that exercise training would alleviate ER stress-associated endothelial dysfunction in atherosclerotic coronary arterioles by reducing ER stress signaling and its downstream cascade including TXNIP/NLRP3 inflammasome." (PMID 34326395, 2021). "Also, we emphasize the current knowledge of the factors that mediate and influence NLRP3-related endothelial dysfunction and potential therapeutic targets, which may be helpful for the treatment of endothelial dysfunction-related diseases." (PMID 32948742, 2020). "Hence, NLRP3 inflammasome-specific pharmacological inhibitors may be the optimal choice for the treatment of endothelial dysfunction, providing a new strategy to treat endothelial dysfunction-related disease." (PMID 32948742, 2020).
endothelial dysfunction (continued). "Plaque instability, immune cell recruitment, and endothelial dysfunction are all influenced by pro-inflammatory cytokines like IL-6 and TNF-α, as well as pathways including NF-κB, TLRs, and the NLRP3 inflammasome." (PMID 40006011, 2025). "Prior studies have shown that NEAT1 promotes endothelial pyroptosis and vascular inflammation through KLF4/NLRP3 signaling, and that exercise downregulates NEAT1 to attenuate endothelial dysfunction in AS." (PMID 41268533, 2025). "The results of this study indicate that Sil can decrease the expression of IL-18, NLRP3, caspase-1, and GSDMD and increase the expression of eNOS to inhibit inflammatory reaction and improve endothelial dysfunction." (PMID 37636019, 2023). "It has been studied that HSYA alleviates AS with suppression VSMC proliferation, endothelial dysfunction, foam cell formation, and platelet activation by regulating PI3K/Akt/TOR, NLRP3 inflammasome, TNFR1/NF-κB and TLR4/Rac1/Akt signaling pathways." (PMID 35493086, 2022). "NLRP3 and NLRP1 are responsible for endothelial dysfunction through the regulation of immune–inflammatory processes in arterial endothelial cells." (PMID 36014040, 2022). "NLRP3 and NLRP1 are involved in endothelial dysfunction through the regulation of immune–inflammatory processes in arterial endothelial cells." (PMID 36014040, 2022). "Endothelial dysfunction due to the NF-kappa B activation is also induced by SAFA, resulting in increased superoxide production, while NLRP3 inflammation activation increases endothelial permeability." (PMID 34354179, 2021). "Routine exercise alleviates endothelial dysfunction in atherosclerotic coronary arterioles in an eNOS, UCP2, and ER stress signaling specific manner, and resulting in reduced TXNIP/NLRP3 inflammasome activity and oxidative stress." (PMID 34326395, 2021). "The endothelial dysfunction evoked by visfatin/eNampt infusion in vivo was also sensitive to both MCC 950 and anakinra treatments, suggesting that the NLRP3-inflammasome-driven tissular release of IL-1β is the final mediator of endothelial damage." (PMID 32214150, 2020). "First, NLRP3 gene deletion prevented testosterone-induced hypercontractility of vascular smooth muscle (VSM) and endothelial dysfunction both in vitro and in vivo." (PMID 32849566, 2020). "Reduced intracellular UA may limit oxidative stress, endothelial dysfunction, and activation of the NOD-like receptor family pyrin domain-containing 3 (NLRP3) inflammasome." (PMID 41301808, 2025). "The oxidative stress activates the vascular NLRP3 inflammasome, exacerbating endothelial dysfunction, the no-reflow phenomenon, and tissue damage during reperfusion." (PMID 40227195, 2025). "Furthermore, the miR‐497‐5p‐mediated NLRP3/caspase‐1/GSDMD pathway and the resulting inflammatory endothelial dysfunction in ox‐LDL‐stimulated HUVECs was also significantly attenuated after UCP2 overexpression." (PMID 40391195, 2025). "Endothelial dysfunction has been characterized by disturbances in nitric oxide (NO) bioavailability, an increase in free radical generation, and increased NLR-family purin-domain-containing 3 (NLRP3) inflammasome activity." (PMID 38542344, 2024). "As AGEs induced endothelial dysfunction, salidroside might play a pivotal role by regulating AMPK/NF-κB/NLRP3 signaling." (PMID 37175869, 2023). "Anagliptin, a new DPP-4 inhibitor approved for treating T2DM, was recently reported to reverse endothelial dysfunction by SIRT1-dependent inhibition of NLRP3 inflammasome activation and suppression of NOX4-ROS-TXNIP-NLRP3 crosstalk, in this way creating scope for additional research." (PMID 37175869, 2023). "As far as we are aware, no information exists to know the role of mitophagy in NLRP3 inflammasome activation and endothelial dysfunction under microgravity conditions." (PMID 35874841, 2022).
endothelial dysfunction (continued). "More recently, in adult mice with metabolic disorders, ROS accumulation results from endothelial dysfunction with decreased TRX and increased NADPH oxidase endothelial expression, leading to oxidative stress and NLRP3 inflammasome activation in the aortic wall." (PMID 33567593, 2021). "We demonstrated that AE inhibited the NLRP3 signaling pathway to alleviate endothelial dysfunction because ZO‐1/2 of gNLRP3 cells has no significant change in the normal group, model group, or administration group." (PMID 32573820, 2020). "From the upregulation of the nod-like receptor protein 3 (NLRP3) inflammasome and the Notch and Wnt pathways to the increased expression of VEGF-A and the downregulation of connexins Cx32, Cx37, and Cx40, these processes contribute further to endothelial dysfunction and plaque formation." (PMID 39941130, 2025). "Indeed, oxidative stress also activates the vascular NLRP3 inflammasome, worsening endothelial dysfunction, the no-reflow phenomenon, and tissue damage during reperfusion." (PMID 40227195, 2025). "The activated NLRP3 inflammasome could increase the expression and release of the high-mobility histone box-1 (HMGB1) in endothelial cells, promoting endothelial hyperpermeability and leading endothelial dysfunction." (PMID 36187801, 2022). "In the present study, we investigated whether EIII exposure would lead to endothelial dysfunction, whether sequential injections of EIII and antiplatelet Ig would elicit hemorrhage in mice, and whether such pathogeneses are Nlrp3 inflammasome–mediated responses." (PMID 33717109, 2021). "Finally, it must be stressed that inflammasomes other than NLRP3, such as AIM2, NLRP1, NLRC4, and NLRP6, have not been thoroughly investigated so far in the context of the development of endothelial dysfunction and the impact on pathogenesis and progression of T2DM." (PMID 33546399, 2021).